CYFIP1 (cytoplasmic FMR1 interacting protein 1)
Description:
Component of the CYFIP1-EIF4E-FMR1 complex which binds to the mRNA cap and mediates translational repression. In the CYFIP1-EIF4E-FMR1 complex this subunit is an adapter between EIF4E and FMR1. Promotes the translation repression activity of FMR1 in brain probably by mediating its association with EIF4E and mRNA (By similarity). Regulates formation of membrane ruffles and lamellipodia. Plays a role in axon outgrowth. Binds to F-actin but not to RNA. Part of the WAVE complex that regulates actin filament reorganization via its interaction with the Arp2/3 complex. Actin remodeling activity is regulated by RAC1. Regulator of epithelial morphogenesis. As component of the WAVE1 complex, required for BDNF-NTRK2 endocytic trafficking and signaling from early endosomes (By similarity). May act as an invasion suppressor in cancers.
Synonyms: Sra-1; KIAA0068; P140SRA-1; SHYC; SRA1
Tractability: Small molecule: a structure with a bound ligand is known; it has a high-quality binding pocket. Antibody: its Gene Ontology location is reachable by antibodies, with high confidence. PROTAC: ubiquitination databases record sites on it; its protein half-life has been measured.
Gene: Protein-coding gene on chromosome 15 (22,867,052 to 22,981,063, reverse strand). Ensembl gene ENSG00000273749.
Subcellular location: Cytoplasm; Cytoplasm, perinuclear region; Cell projection, lamellipodium; Cell projection, ruffle; Synapse, synaptosome
Pathways (Reactome):
Signal Transduction: RAC1 GTPase cycle; RAC2 GTPase cycle; RAC3 GTPase cycle; RHO GTPases Activate WASPs and WAVEs; RHOG GTPase cycle; VEGFA-VEGFR2 Pathway
Immune System: Neutrophil degranulation; Regulation of actin dynamics for phagocytic cup formation
Disease: FCGR3A-mediated phagocytosis
Gene Ontology:
Molecular function: protein binding; small GTPase binding; actin filament binding; RNA 7-methylguanosine cap binding; translation repressor activity
Biological process: axon extension; cognition; positive regulation of Arp2/3 complex-mediated actin nucleation; positive regulation of lamellipodium assembly; Rac protein signal transduction; axon guidance; lamellipodium assembly; negative regulation of translation; regulation of translation; ruffle organization; dendrite extension; neuron projection development; positive regulation of neurotrophin TRK receptor signaling pathway; regulation of actin filament polymerization; regulation of modification of postsynaptic actin cytoskeleton; regulation of translation at postsynapse, modulating synaptic transmission
Cellular component: excitatory synapse; extracellular exosome; focal adhesion; SCAR complex; translation repressor complex; cytoplasm; cytosol; extracellular region; lamellipodium; neuron projection; perinuclear region of cytoplasm; ruffle; secretory granule lumen; specific granule lumen; synapse; tertiary granule lumen; cell leading edge; postsynapse
Genetic constraint (gnomAD): Loss-of-function variants: 52 observed, 148.98 expected, observed/expected ratio (o/e) 0.35, 90% interval 0.28 to 0.44. The upper end of that interval is the gene's LOEUF score, 0.44, which puts it in group 1 of 6, group 1 being the genes least tolerant of losing a copy. Missense variants: 1,275 observed, 1,622.8 expected, observed/expected ratio (o/e) 0.79, 90% interval 0.75 to 0.82. Synonymous variants: 627 observed, 646.67 expected, observed/expected ratio (o/e) 0.97, 90% interval 0.91 to 1.04.
Homologues: Orthologues: chimpanzee CYFIP1 (99% identical), macaque CYFIP1 (99% identical), rabbit CYFIP1 (99% identical), dog CYFIP1 (99% identical), rat Cyfip1 (99% identical), mouse Cyfip1 (99% identical), guinea pig CYFIP1 (99% identical), pig CYFIP1 (95% identical), zebrafish cyfip1 (93% identical), tropical clawed frog cyfip1 (92% identical), Drosophila melanogaster Cyfip (67% identical), Caenorhabditis elegans gex-2 (52% identical). Paralogues in human: CYFIP2 (88% identical).
Diseases named in the same sentence as CYFIP1 in open-access papers:
CYFIP1 is named in the same sentence as 68 diseases in open-access papers, as found by Europe PMC text mining. Sharing a sentence is not in itself a finding about the gene and the disease. The quoted sentences say what the papers report.
autism (42 papers, 2008 to 2026). Persistent deficits in social interaction and communication and interaction as well as a markedly restricted repertoire of activity and interest as well as repetitive patterns of behavior. "The CYFIP1 gene is located in a chromosomal region linked to various neurological disorders, including intellectual disability, autism, and schizophrenia." (PMID 40642607, 2025). "In silico analyses for the four coding genes of NIPA1, NIPA2, CYFIP1, and TUBGCP5 in the 15q11.2 region suggested cardinal disease associations of NIPA1‐Spastic paraplegia 6, NIPA2‐PWS/AS, CYFIP1‐fragile X syndrome and autism, and TUBGCP5‐AS." (PMID 37013615, 2023). "Cyfip1, the gene encoding cytoplasmic FMR1 interacting protein 1, has been of interest as an autism candidate gene for years." (PMID 37545882, 2023). "Copy number variation (CNV) at the 15q11.2 region has been identified as a significant risk locus for autism, including a gene coding for CYFIP1 (cytoplasmic FMR1 interacting protein 1)." (PMID 36545727, 2023). "One important interactive gene involved in this cytogenetic region and is associated with learning and motor delays, autism and schizophrenia is CYFIP1, which encodes a protein involved with actin cytoskeletal dynamics." (PMID 36901699, 2023). "CYFIP1, here hypermethylated in 8% of the cases, was previously associated with schizophrenia and autism through CNVs and is known to regulate the balance between synaptic excitation and inhibition." (PMID 33892787, 2021). "CYFIP1 is a genetic risk factor for schizophrenia, autism and developmental delay, by virtue of its presence in the penetrant 15q11.2(BP1–BP2) copy number deletion." (PMID 34031371, 2021). "We generated Nlgn3y/−Cyfip1+/− double-mutant mice to investigate the effect of the Nlgn3/Cyfip1 pathway on phenotypes associated with autism: changes in behavior and dendritic spine density." (PMID 32669345, 2020). "Many of these rearrangements are associated with abnormal phenotypes including seizure, developmental delay and autism, but deletions affecting CYFIP1 typically cause a worse phenotype, compared to deletions in these regions not involving CYFIP1." (PMID 32486060, 2020). "Three of the patients with de novo SHANK2 mutations were also found to have deletions of CHRNA7 and cytoplasmic FMR1 interacting protein 1 (CYFIP1) – both previously implicated in ASD – supporting a “multiple-hit” model of autism." (PMID 31481879, 2019). "Multiple CYFIP1 regulatory variants independent from rs4778298 / rs66903469 have been associated with increased risk for schizophrenia and autism." (PMID 27351196, 2016). "Knockdown or overexpression of CYFIP1 impacts neuronal morphology, brain development and function and common CYFIP1 regulatory variants have been associated with schizophrenia and autism." (PMID 27351196, 2016). "Copy number variation (CNV) at the 15q11.2 region, which includes a gene that codes for CYFIP1 (cytoplasmic FMR1 interacting protein 1), has been implicated in autism, intellectual disability and additional neuropsychiatric phenotypes." (PMID 22900020, 2012). "Patients with the larger class I deletions that encompass the locus for the FRMP interacting protein CYFIP1 appear to have an increased risk for autism as compared to patients with class II deletions." (PMID 21235769, 2011). "High expression of CYFIP1 due to gene duplication has been associated with autism." (PMID 34539327, 2021). "Many of these genes, including neuroligins, neurorexin 1, PTEN, PSD95, MAPK1, JAKMIP, SHANK3, and CYFIP1, are linked to autism when they are mutated, which may explain the high comorbidity that exists between FXS and ASD." (PMID 34926684, 2021). "Cardinal diseases that are associated with the CYFIP1 gene are Fragile X Syndrome and Autism." (PMID 32384786, 2020).
autism (continued). "In humans, either increases or decreases in CYFIP1 gene dosage are risk factors for intellectual disability, autism, and schizophrenia, and deletions in chromosome 15 that include CYFIP1 are associated with increased symptom severity in Prader–Willi and Angelman syndromes." (PMID 33613257, 2020). "Copy number variations in CYFIP1 are associated with autism, schizophrenia, and intellectual disability, but its role in regulating synaptic inhibition or E/I balance remains unclear." (PMID 30784587, 2019). "This interaction appears to mediate subsequent interactions with a network of other autism-related genes’ protein, including CYFIP1, MAPT, APBB1, SNAP25, and CDK16." (PMID 39376742, 2024). "A study on CYFIP1 mRNA expression in human dorsolateral prefrontal cortex revealed higher expression of CYFIP1 mRNA in ASD and classical autism patients, and identified several common variants of CYFIP1 in these patients." (PMID 32244264, 2020). "Human Cytoplasmic FMR1 Interacting Protein 1 (CYFIP1) is reported to be involved in neurodevelopmental disorders, such as intellectual disorder, autism, schizophrenia, epilepsy, and Burnside–Butler syndrome." (PMID 31438473, 2019). "For other genes, such as SNRPN, CYFIP1, and ATP10A, a few SNPs or haplotypes were found to be nominally associated with autism in Europeans20,24–26." (PMID 30108208, 2018). "Nine SNPs (rs8025849 in NIPA1, rs3812922 in NIPA2, rs1009153 and rs2289818 in CYFIP1, rs8037745 in SNRPN, rs12438141 and rs1863467 in GABRB3, rs7403021 and rs7180500 in GABRG3) were nominally associated with autism under the recessive model (p < 0.05)." (PMID 30108208, 2018). "Since dFMR1 and CYFIP1 are candidates for ID and autism, these studies on the fly pave the way to deeper and more refined studies in mice and in humans." (PMID 29713264, 2018). "Cytoplasmic FMRP interacting protein 1 (CYFIP1) is a candidate gene for intellectual disability (ID), autism, schizophrenia and epilepsy." (PMID 28183735, 2017). "The CYFIP1/SRA1 gene is located in a chromosomal region linked to various neurological disorders, including intellectual disability, autism, and schizophrenia." (PMID 24050404, 2013). "While autism is a heterogeneous disorder with multiple genetic and perhaps environmental factors contributing to the etiology; the CYFIP1 gene continues to show a molecular link between PWS, PWP in FXS, and autism." (PMID 22043169, 2011). "Altered expression of CYFIP1 has also been reported both in autism patients with maternal duplication of 15q11-q13 and in fragile X syndrome patients with autistic features." (PMID 18226259, 2008). "This extends the idea that reduced myelination in Cyfip1+/− rats results in impaired brain network function, which in turn leads to cognitive impairment consistent with behavioural deficits seen in neurodevelopmental disorders such as autism and schizophrenia." (PMID 38876996, 2024). "In humans, copy number variations in CYFIP1 appear to have sweeping physiological and structural consequences in the brain, either producing or altering the severity of intellectual disability, autism, and schizophrenia." (PMID 33613257, 2020). "In rodents, Cyfip1 manipulation has strong anatomical, cellular, and physiological consequences that overlap mechanistically with cell signaling pathways employed by other genes relevant to intellectual disability, autism, and schizophrenia." (PMID 33613257, 2020). "The reduced expression of CYFIP1 mRNA may provide an obstacle in the neuronal plasticity of the brain resulting in the manifestation of higher rates of autism due to the dysregulation of neuronal connections." (PMID 22043169, 2011). "Together, these results implicate Cyfip1 in development or maintenance of cortico-limbic-striatal network integrity, further supporting the hypothesis that alterations in this circuitry contribute to behavioural inflexibility observed in neuropsychiatric diseases including schizophrenia and autism." (PMID 38876996, 2024).
autism (continued). "In a recent study of those with FXS and autism and in those with autism secondary of a 15q duplication, there was abnormal expression of GPR155 (G protein coupled receptor 155) in both groups which is a gene regulated by CYFIP1." (PMID 22043169, 2011). "Among the interactors of FMRP, CYFIP1/2 (cytoplasmic FMRP interacting protein) proteins are good candidates for ID and autism, on the bases of their genetic implication and functional properties, even if the precise functional significance of the CYFIP/FMRP interaction is not understood yet." (PMID 24733999, 2014).
schizophrenia (33 papers, 2011 to 2026). A major psychotic disorder characterized by abnormalities in the perception or expression of reality. "CYFIP1 was reported to be associated with brain diseases such as schizophrenia and autism spectrum disorders." (PMID 36036011, 2022). "This assertion is, in part, based on a genetic risk modeling experiment for schizophrenia in which dysfunction of the AP adhesion and polarity factor CYFIP1 led to delamination and ectopic localization of aRGCs." (PMID 35281509, 2022). "Numerous studies have identified a loss of CNVs on 15q11.2 in individuals with schizophrenia, and polymorphisms and rare variants in CYFIP1 are also found to be associated with susceptibility to schizophrenia." (PMID 34746116, 2021). "CYFIP1 deletion in 15q11.2 syndrome increases risk for developmental disorders including schizophrenia." (PMID 31198525, 2019). "In humans, copy-number variants of the CYFIP1 gene have been associated with autism spectrum disorders and schizophrenia." (PMID 31371726, 2019). "Recent research has also shown that reduced CYFIP1 expression leads to dysregulation of schizophrenia- and epilepsy-associated gene networks." (PMID 30909440, 2019). "Previous work using human neural progenitor cells has found that reduced CYFIP1 expression caused dysregulation in schizophrenia- and epilepsy-associated gene networks." (PMID 30909440, 2019). "In summary, 25 proteins out of 40 identified in our CYFIP1 interactome are encoded by genes involved in diseases: 26% are associated with schizophrenia, 19% with ASD, and 10% with ID." (PMID 24050404, 2013). "CYFIP1 dysregulation has been associated with neuropsychiatric disorders, such as intellectual disability, schizophrenia (SCZ), and autism spectrum disorders (ASD), and plays an important role in the invasion and metastasis of tumors, such as breast, prostate, and colon cancers." (PMID 38427078, 2024). "Among these genes, the researchers have found that CYFIP1 plays an important role in brain functional connectivity and corpus callous function, suggesting that copy number variation in the human CYFIP1 gene is associated with autism spectrum disorder and schizophrenia." (PMID 36544768, 2022). "Other gene such as CYFIP1 in the 15q11.2 region may also play a role in contributing to neurodevelopment and psychiatric illness because of copy number variant of 15q11.2 including CYFIP1 has been associated with schizophrenia." (PMID 23967326, 2013). "Likewise an FMRP-associated gene,CYFIP1, containing a rare micro-deletion was found in a recentstudy of copy number variants in schizophrenia." (PMID 21559497, 2011). "The human CYFIP1 gene is linked to Autism Spectrum Disorder (ASD) and Schizophrenia (SCZ), both associated with brain connectivity defects and corpus callosum abnormalities." (PMID 41315480, 2025). "Mutations in the CYFIP1 gene are associated with the severe ASD-related Angelman and Prader-Willi syndromes, as well as ASD and schizophrenia." (PMID 37928069, 2023). "The relevance of CYFIP1 to schizophrenia becomes especially apparent when considered in the wider context of its biological actions within protein complexes." (PMID 34883502, 2020). "Consistent with the genetic findings, proteomic analysis of prefrontal cortex post-mortem tissue from schizophrenia patients revealed altered levels of CYFIP1 and other proteins belonging to protein synthesis pathways." (PMID 34883502, 2020). "CYFIP1 was first associated with schizophrenia in studies that showed an enrichment of the ARC complex (containing 25 genes, of which CYFIP1 is one) in de novo CNV deletions from patients with schizophrenia." (PMID 34883502, 2020).
schizophrenia (continued). "CNVs of the cytoplasmic FMR1-interacting protein 1 (CYFIP1) was found to be associated with ASD and other neuropsychiatric disorders such as schizophrenia." (PMID 32661244, 2020). "Copy-number variants of the CYFIP1 gene in humans have been linked to autism spectrum disorders (ASD) and schizophrenia (SCZ), two neuropsychiatric disorders characterized by defects in brain connectivity." (PMID 31371726, 2019). "Providing direct support for involvement of CYFIP1 in BP1-2 mediated neurodevelopmental disease (NDD), we observed marked dysregulation of schizophrenia and epilepsy risk genes, disorders associated with the deletion." (PMID 26824476, 2016). "CYFIP1 deletions have been reported in CNV analyses of schizophrenia." (PMID 34321086, 2021). "CYFIP1 interacts with fragile X mental retardation protein (FMRP; absent FMRP causes fragile X syndrome); reduced CYFIP1 in human neural progenitors results in the dysregulation of the schizophrenia and epilepsy gene networks." (PMID 34680874, 2021). "Importantly, both CYFIP1 and CYFIP2 genes are associated with various types of brain disorders, including autism spectrum disorders, intellectual disability, schizophrenia, and epilepsy, suggesting critical roles of CYFIP1 and CYFIP2 in proper brain development and function." (PMID 32917241, 2020). "Moreover, mutations in each gene were associated with different disorders: NIPA1 with autosomal-dominant hereditary spastic paraplegia, NIPA2 with childhood absence epilepsy, TUBGCP5 with ADHD and obsessive-compulsive disorder, and CYFIP1 with increasing susceptibility to ASD and with schizophrenia." (PMID 30583851, 2019). "Moreover, reduced CYFIP1 also disrupted normal expression of fragile X mental retardation protein (FMRP) targets and postsynaptic density (PSD) genes, each previously implicated in schizophrenia." (PMID 26824476, 2016). "Furthermore, the genetic association with schizophrenia of FMRP targets (section “FMRP and FMRP Targets in Psychiatric Genomic Studies”), which are regulated by the CYFIP1-FMRP complex, lends additional evidence to the relevance of CYFIP1 to schizophrenia." (PMID 34883502, 2020). "Also, overlap of some of the modules with the gene expression signatures of those found in schizophrenia, bipolar disorder, Dup15q, and ASD, demonstrating that the effect of CYFIP1 overexpression affects pathways observed across several psychiatric disorders." (PMID 31198525, 2019). "Genes implicated in schizophrenia and epilepsy, but not conditions unrelated to BP1-2 deletions, are overrepresented among CYFIP1 knockdown dysregulated mRNAs." (PMID 26824476, 2016). "In the absence of CYFIP1, its epistatic interaction with ACTR2 (a mediator of WAVE signaling) is abolished, leading to susceptibility of neuropsychiatric disorders, including schizophrenia." (PMID 35281509, 2022).